IL17A (interleukin 17A)
Diseases named in the same sentence as IL17A in open-access papers (continued):
Sharing a sentence is not in itself a finding about the gene and the disease.
malaria (continued). "Measurement of IL-17A levels allowed to distinguish the co-infected patients from both VL and malaria mono-infected counterparts, indicating that both diseases synergistically concurred to its up-regulation." (PMID 24886212, 2014). "Increase in co-infected patient IL-17A level appeared to be mainly triggered by malaria, as the difference with this group reduced after age and parasitaemia matching, but persisted towards VL patients in women only and in subjects older than 15 years." (PMID 24886212, 2014). "Up-regulation of pro-inflammatory IL-17A distinguished the co-infected patients from both VL and malaria mono-infection cases (P <0.05), indicating that synergistic interactions of the two diseases upon each other concurred to its release." (PMID 24886212, 2014). "The use of principal component analysis and cluster analysis associated increased levels of IL-6, TNF-α, IL-10, and CRP and low levels of IL-17A predominantly with individuals with malaria alone and coinfected individuals." (PMID 25309052, 2014). "As anticipated, all cytokines assessed were significantly elevated in malaria patients compared to controls, especially IL-17A in complicated malaria." (PMID 21658247, 2011). "A significant reduction in IL-17A expression was noted in the regional lymph nodes in the EAE-malaria group in comparison to the EAE group." (PMID 21464982, 2011). "This indicates that IL-17A has an essential regulatory role in malaria infection, controlling the intensity of the immune response, as described in the experimental model, as well as human malaria and several other infectious diseases." (PMID 38438955, 2024). "To understand the specific IL-17A roles in malaria infection, we conducted this work to analyse IL-17A levels in a retrospective Senegalese cohort, including healthy controls and severe and uncomplicated malaria subjects." (PMID 38438955, 2024). "IL-17A is a multifunctional cytokine which has a protective role in immunity for the clearance of intracellular pathogens such as Plasmodium spp., making it a good therapeutic biomarker in malaria diseases." (PMID 38438955, 2024). "We IL-17A rs3819024 G could also be considered a biomarker of malaria severity." (PMID 38438955, 2024). "Nonetheless, the increased levels observed in the asymptomatic malaria group may indicate that IFN-γ and IL-17A are associated with on-going inflammation which has a significant impact on disease pathogenesis as well as the development of anti-disease immunity." (PMID 33281757, 2020). "In contrast, Kisumu children had similar frequencies of cytokine responders to the EBV and malaria antigens used in our assay, while children diagnosed with eBL had significantly more CD4+ T cell IL-17A responders to EBNA1 compared to PfSEA-1A (p = 0.0004)." (PMID 34771539, 2021). "Children with either microscopic or submicroscopic asymptomatic malaria exhibited higher levels of IFN-γ, IL-17A, and IL-4 compared to uninfected controls." (PMID 33281757, 2020). "Most remarkably, Malaria group presented the highest levels of CRP and intestinal parasites the highest level of IL-12p70, IL-17A, and NO." (PMID 25309052, 2014). "Circulating levels of interferon (IFN)-γ, interleukin (IL)-2, IL-4, IL-6, IL-10, IL-12p70, IL-13, IL-17A and tumor necrosis factor (TNF) were assessed in sera of patients infected with active VL and/or malaria and healthy individuals from Gedarif State, Sudan." (PMID 24886212, 2014). "In addition, eBL children seem to have developed more IL-17A expressing CD4+ and CD8+ T cells compared to Kisumu children who also resided in malaria holoendemic areas." (PMID 34771539, 2021). "We observed increased levels of cytokines such as TNF-α and IL-6 in children with microscopic asymptomatic malaria, whereas, IFN-γ, IL-17A, and IL-4 levels were increased in infected children with microscopic or submicroscopic asymptomatic malaria compared with uninfected controls." (PMID 33281757, 2020).
malaria (continued). "Clinical malaria cases exhibited an immunological profile qualitatively similar to that of the VL patients, with increased concentrations of TNF, IL-6 and IL-10 (P <0.0001) and, to a less extent, IFN-γ and IL-17A (P <0.01), IL-4 and IL-12p70 (P <0.05)." (PMID 24886212, 2014). "However, for the malaria group, four distinct correlation patterns were observed; first pattern (CCL4, CCL2, CCL3, IL12 and IL2), second pattern (IL-17A, IL-1β, CCL11, IL4), third pattern (IL5, IL7, IL13), and fourth pattern (IL1RA, CXCL10, TNFα, IL2R, CXCL9, IL6)." (PMID 35811678, 2022). "Using a bespoke flow cytometry assay we measured intracellular IFN-γ, IL-10, IL-17A expression and phenotyped CD4+ and CD8+ T cell effector memory subsets specific to EBNA1 for eBL patients compared to two groups of healthy children with divergent malaria exposures." (PMID 34771539, 2021). "For malaria infected individuals (M and CI) the profile was high levels of IL-1β, IL-6, TNF-α IL-10, and CRP and decreased levels of IL-17A while for malaria negative individuals (IP and UN) the profile was high levels of IL-17A, NO and decreased levels of IL-10 and CRP." (PMID 25309052, 2014). "However, the role of IL-17A in malaria has not yet been extensively investigated." (PMID 38438955, 2024). "Likewise, the negative correlation observed between Granzyme B and IL-17A may have resulted from the low levels of granzyme B observed in malaria-infected children." (PMID 33281757, 2020). "Malaria infection in the collected maternal peripheral, placental, umbilical cord samples was determined microscopically, and ELISA was used to measure the plasma levels IL-4, IL-6, IL-10, IL-17A, and INF γ in the collected positive and negative malaria samples." (PMID 33422078, 2021).
Granuloma (115 papers, 2010 to 2026). A compact, organized collection of mature mononuclear phagocytes, which may be but is not necessarily accompanied by accessory features such as necrosis. "A well described function of IL-17A is the recruitment of neutrophils, which appears, in the context of experimental TB, to be associated with the early development of granulomas." (PMID 35116036, 2021). "In contrast, higher levels of IL-17A are associated with a development of an early protective immunity and the formation of mature granulomas in Mtb infection." (PMID 33613521, 2020). "Also, granuloma formation was impaired in an IL-17A-deficient mouse model of sarcoidosis." (PMID 34021178, 2021). "IL-17A-expressing cells were most commonly found in areas of granuloma formation in histopathological material." (PMID 40217830, 2025). "From this point on, the T cells are the ones pathologically dictating the creation of the granuloma, releasing the highly granuloma-associated conception cytokines IFN-γ, IL-17A and IL-2, leading to the circulation of other cell types." (PMID 40002701, 2025). "IL-17A is instrumental in granuloma formation and stability and recall of IFN-γ–producing CD4+ T cells to the lungs." (PMID 38165044, 2024). "From this characterisation it was observed that stage I early granulomas expressed more IL-17A and IL-10 when compared to late-stage granulomas (stage IV)." (PMID 37901102, 2023). "Regarding IL-17 in sarcoidosis, it was reported that the primary Th17-cytokine, IL-17A, is an important mediator of granuloma formation and maturation." (PMID 35141260, 2022). "Similarly, the increased production of IL-17A in mice with a deficiency of the specific IL-27 receptor subunit IL-27Rα mediated protection against Mtb accompanied by the formation of highly organized granulomas and an accumulation of multifunctional CD4+ T cells in the lung." (PMID 36139450, 2022). "In these mice, IL-17A mediates the quality of protective T cell immune responses and the formation of highly stratified granulomas in the infected lungs." (PMID 36139450, 2022). "With regard to IL-17A expression in the lung, immune cells expressing this cytokine were augmented in egg-induced perivascular granulomas of both HIV and Wt mice but more markedly in HIV mice, both around and within vessels." (PMID 35954255, 2022). "IL-17A mRNA expression is upregulated in granulomas of all stages with one study showing increased expression associated with stages I/II compared to stages III/IV pulmonary granulomas." (PMID 35056009, 2022). "In contrast, expression of IL-17A mRNA was greater in granulomas of the tracheobronchial lymph node compared to the lung." (PMID 35056009, 2022). "Studies of IL-17A in bTB have demonstrated its role in immunity against mycobacterial infection, in addition to participation in granuloma formation." (PMID 33746980, 2021). "Increased IL-17A+ cells were also observed in the lamina propria from biopsies containing granulomas compared with those from biopsies from healthy controls or non-granulomas biopsies." (PMID 33912164, 2021). "In the absence of IL-27Rα, Mtb-infected lungs exhibit highly structured granulomas surrounded by a lymphocyte rim which predominantly contains clusters of B cells - an effect that is strikingly dependent on the expression of IL-17A." (PMID 35116036, 2021). "While IL-12A was significantly upregulated in cysts (P < 0.01), IL-17A represents the highest significantly upregulated gene in granulomas (P < 0.0001)." (PMID 34539639, 2021). "Accordingly, in Mtb-infected IL-27Rα-/- mice, IL-17A mediates the early accumulation of neutrophils in the centres of organized granulomas." (PMID 35116036, 2021). "Representative TB-infected tissue containing typical granulomas or incipient granulomas was incubated with anti-IL-17A and anti-tryptase antibodies followed by a fluorescent staining." (PMID 34021178, 2021).
Granuloma (continued). "The authors found that IL-17A−/− mice showed impairments in developing mature granulomas 28 days after BCG infection in the lung." (PMID 33273606, 2020). "Our results indicate that IL-17A-producing γδ T cells are involved in the processes of granuloma and fibrosis, although the abundance of the cells was relatively low." (PMID 32611373, 2020). "IL-17A knockout and IL-17A neutralizing antibody alleviated inflammation in the lung of mice with PA-induced granulomatosis, blocked loose sarcoidosis-like granuloma development, and reduced inflammatory factor levels in peripheral blood and BALF." (PMID 31474992, 2019). "Within the lung, gene expression was significantly greater within granulomas compared to non-granuloma areas for IL-17A, IFN-γ and TGF-β." (PMID 27902779, 2016). "In contrast, expression of IL-17A was greater in granulomas of the tracheobronchial lymph nodes compared to those of the lung." (PMID 27902779, 2016). "Although mycobacterial infection induced histopathological changes in the lungs of both the wild‐type C57BL/6 and IL‐17A KO mice, the granuloma number and size were smaller in IL‐17A KO mice than in wild‐type C57BL/6 mice." (PMID 27980775, 2016). "We have identified the central roles of both IL-17A and neutrophils in the pathogenesis of granuloma formation in acute HP." (PMID 26367130, 2015). "In necrotizing granulomas, γδ T cells expressing Il17a were identified." (PMID 40843005, 2025). "IL-17A and Th17 cells participate in granuloma formation and fibrosis in HP and sarcoidosis." (PMID 39464896, 2024). "In addition, IL-17A is involved in the formation of granulomas by increasing chemokine production, which helps recruit inflammatory cells migrating to the infection site." (PMID 36795721, 2023). "Moreover, using ISH, MGCs of early stage I granulomas were shown to express more IL-17A and IL-10, and less TGF-β than MGCs of late-stage IV granulomas." (PMID 35056009, 2022). "In addition, IL-17A participates in the formation of mature granuloma in the lungs during M. tuberculosis infection, which plays a key role in the prevention of M. tuberculosis spread." (PMID 34074345, 2021). "Notably, as granulomas developed, expression decreased until there was significantly less IL-17A in more advanced compared to early-stage lesions." (PMID 33746980, 2021). "After 13 weeks of treatment, the increase in the IL-17A level in some mice was conducive to the formation of granulomas and limited the spread of M. tuberculosis, which may also be one of the reasons for the reduced pathological damage in the NBXH group." (PMID 34074345, 2021). "In addition to TNF-α or IFN-γ, IL-17a contributes to the formation of granulomas against mycobacterial infection." (PMID 33273606, 2020). "In summary, the results obtained in the present study demonstrated that IL-17A and MMP-9 were expressed in the granuloma of different mycetoma causative agents and that the expression of IL-17A was more extensively in larger leasions and lesions with a longer disease duration." (PMID 31295246, 2019). "As with M. mycetomatis, A. pelletieri and S. somaliensis mycetoma, the N. brasiliensis granuloma is characterized by neutrophils and the high expression of IL-17A in the beginning of the infection could be responsible for the recruitment of neutrophils." (PMID 31295246, 2019). "It is therefore impossible to determine the precise function of IL-17A and MMp-9 in the formation of the mycetoma granuloma, we could only determine their presence." (PMID 31295246, 2019). "We aimed to establish a simple and practical mouse model of sarcoidosis-like granulomatosis that resembles human sarcoidosis, and used IL-17A−/− mice and IL-17A neutralizing antibody to further investigate the role of IL-17A in sarcoidosis granuloma development." (PMID 31474992, 2019). "IL-17A plays an important role in experimental sarcoidosis-like granuloma formation." (PMID 31474992, 2019).
Granuloma (continued). "Furthermore, the granulomas in the lungs of IL‐17A KO mice were less densely packed with mononuclear cells compared to those of wild‐type C57BL/6 mice." (PMID 27980775, 2016). "In summary, the results in the current study indicated that both the IL-17A–CXCL5 pathway and neutrophils play important roles in granuloma formation in the setting of acute HP and the increase in IL-17A expression stimulates the recruitment of neutrophils to the lungs via the IL-17A–CXCL5 pathway." (PMID 26367130, 2015). "However, LBR5, LBR6 and LBR8 induced increased levels of pro-inflammatory cytokines (IFN-γ, IL-2, IL-6, TNF-α and IL-17A), which are consistent with a robust Th1 immune response that especially promotes cellular proliferation and the formation of granulomas (IFN-γ and TNF-α)." (PMID 34046037, 2021). "Although Th17 cells are associated with aggravation of the pathology in murine model of S. mansoni infection, the high levels of IL-17A and IL-10 may reflect in the regulation of Th2 response, reducing the granuloma size and inflammation, and more efficient granuloma resolution." (PMID 32853206, 2020). "Therefore, increased production of IL-17A could be beneficial in to hamper the mycobacterial infection contributing in formation of mature granuloma and blocking disease progression." (PMID 26840977, 2016). "These kind of granulomas can cause severe tissue damage and it may be suggested that the production of 1,25(OH)2D3 is part of a negative feed-back mechanism to reduce tissue damage, as 1,25(OH)2D3 both inhibits IFN-γ and IL-17A production and induces a shift from M1 towards M2 macrophages." (PMID 34621269, 2021). "We observed that RNA expression of IL-7, IL17A, IL6, MARCO, IFN-γ, and IL-8 was significantly decreased in granulomas treated with α-MSH compared to the controls." (PMID 32350353, 2020). "In this study we demonstrated that IL-17A and MMP-9 were expressed in the mycetoma granuloma but at different zones surrounding the grain." (PMID 31295246, 2019). "Also in mycetoma lesions both MMP-2 and MMP-9 are expressed at the site of infection, however to date there is no data indicating whether a Th17 response plays a role in the mycetoma granuloma formation and if there is a correlation between IL-17A expression and MMP expression in mycetoma lesions." (PMID 31295246, 2019). "Neither granuloma nor fibrosis was observed in IL-17A-knockout mice, even in the presence of IFN-γ enhancement." (PMID 40724901, 2025). "No granulomas were found in the IL-17A knockout mice group, whereas granulomatous inflammation in the other group was observed." (PMID 40217830, 2025). "In IL-17A–knockout mice, M. tuberculosis infection is accompanied by granuloma that failed to mature (partially due to reduced intercellular adhesion molecules and LFA-1) and impaired protective response." (PMID 38165044, 2024). "An unknown antigen is first presented to CD4+ T-lymphocytes that trigger T-helper 17 (Th17)-related cytokines, interleukin-17A (IL-17A), regulatory T-cells, and tumor necrosis factor (TNF), a proinflammatory cytokine, to produce granulomas." (PMID 38202248, 2023). "Notably, these cells were strongly augmented in perivascular granulomas of both mice but more markedly in HIV mice, with IL-17A+ cells being detected both around and within the vessel." (PMID 35954255, 2022). "It is also unclear whether MC cytokines, e.g. IL-17A, and TGF-β contribute to the inflammatory process, and formation and maintenance of granulomas and fibrogenesis." (PMID 34021178, 2021). "IL-17A was the highest positively correlated gene to periapical granuloma, while TLR2, TLR4, VEGF, and MMP-9 were negatively correlated with the enriched pathways of granuloma." (PMID 34539639, 2021). "Since not all cellular targets of IL-17A (e.g. neutrophils) are present in the Mtb-induced, in-vitro granulomas, a potential in-vivo effect of its blocking cannot be completely ruled out." (PMID 32069329, 2020).
Granuloma (continued). "However, since we only demonstrated expression, more studies are needed to determine the roles of IL-17A and MMP-9 in the granuloma formation and to provide further insights in the mycetoma immunopathogenesis." (PMID 31295246, 2019). "For IL-17A, expression in granulomas of only tracheobronchial lymph nodes was greater than that seen in uninfected caudal mediastinal lymph nodes." (PMID 27902779, 2016). "In spite of microscopic morphological similarities, significant differences were seen between late stage granulomas of the lung compared to those of the tracheobronchial lymph nodes for IL-17A, IFN-γ, TGF-β, IL10 and IL-22 but not for TNF-α." (PMID 27902779, 2016). "In addition, TGF-β (p = 0.001), IL-17A (p = 0.007) and its receptor (IL-17AR) (p = 0.009) representing TH17 were significantly up-regulated in the group with severe granulomas as were arginase and IgM." (PMID 20507624, 2010). "Infection with M. bovis strain 534 and treatment with IL-17A neutralizing antibodies did not affect mouse survival but produced a significant increase in bacillary load and a non-significant decrease in inflammatory infiltrate and granuloma area." (PMID 39024223, 2024). "Moreover, the generation of highly stratified granulomas in the Mtb-infected IL-27Rα-/- mice is strikingly dependent on IL-17A, which is not surprising given that the impact of IL-17A on TB granuloma formation has been described before." (PMID 35116036, 2021). "So far, in vitro testing with peripheral blood mononuclear cells infected with Mycobacterium tuberculosis treated with anti-TNF and IL-17A inhibition showed that anti-IL-17A treatment in vitro did not reverse M. tuberculosis dormancy in a human granuloma model." (PMID 28149838, 2017). "Additionally, significant differences were noted between granulomas from two different thoracic lymph nodes that both receive afferent lymphatics from the lungs (i.e., tracheobronchial and caudal mediastinal lymph nodes) for TNF-α, IL-17A, IFN-γ, TGF-β and IL-10 but not for IL-22." (PMID 27902779, 2016).